HLA-C (major histocompatibility complex, class I, C)
Diseases named in the same sentence as HLA-C in open-access papers (continued):
Sharing a sentence is not in itself a finding about the gene and the disease.
AIDS (29 papers, 2007 to 2026). A syndrome resulting from the acquired deficiency of cellular immunity caused by the human immunodeficiency virus (HIV). "In the original analysis, the different allotypes were binary divided into stable and unstable, revealing a significant correlation between rapid progression to AIDS and the presence of unstable HLA-C variants." (PMID 41459481, 2025). "Our results showed a significant correlation between rapid progression to AIDS and the presence of two or one unstable HLA-C variants (p-value: 0.0078, p-value: 0.0143, respectively)." (PMID 36499177, 2022). "In HIV infection, HLA-C allotypes with a high expression were associated with increased T cell responses and slower progression to AIDS, while higher HLA-C expression was also linked with susceptibility to Crohn’s disease." (PMID 35587797, 2022). "To further understand the impact of HLA-C polymorphism on CR development among Brazilian patients with AIDS, we evaluated the HLA-C allele polymorphism in patients presenting or not CR." (PMID 30245869, 2018). "Additionally, a whole-genome association study indicated that a variant located 35 kb upstream of the HLA-C gene (rs9264942) is associated with HLA-C mRNA expression and AIDS progression." (PMID 40877317, 2025). "This study investigated the correlation between unstable HLA-C variants and AIDS progression, giving new insights and broadening knowledge that could be useful for HIV-1 treatment approaches." (PMID 36499177, 2022). "Here we report that stable HLA-C alleles associate with slower progression toward AIDS." (PMID 36499177, 2022). "The present results expand the knowledge about the impact of HLA-C alleles on CR susceptibility; however, the major limitation of this cross-sectional study is the number of patients with AIDS exhibiting CR, a condition that has been drastically decreased due to the availability of ART." (PMID 30245869, 2018). "HLA-C alleles have been associated with protection against AIDS development, particularly for patients exhibiting the -35C allele upstream of the HLA-C gene, which has been reported to be associated with high cellular expression of HLA-C molecules and protection against HIV." (PMID 30245869, 2018). "Further studies encompassing larger groups of patients with AIDS exhibiting CR as well as the study of the complete HLA-C gene could unravel the role of the gene in the susceptibility to CR." (PMID 30245869, 2018). "Furthermore, individuals with HLA-C allotypes that have genetically determined high cell-surface expression, progress more slowly to AIDS and control the viral load significantly better than individuals with low HLA-C expressing alleles." (PMID 23189078, 2012). "Additionally, in our previous studies we reported that stable HLA-C alleles are associated with lower viral loads and more effective immune responses, supporting our finding that unstable alleles contribute to a faster progression to AIDS." (PMID 41459481, 2025). "We analyzed the magnitude of HLA-A-restricted, HLA-B-restricted, or HLA-C-restricted T-cell responses under cART in AIDS patients." (PMID 37877716, 2023). "GWAS studies found that SNP rs9264942 located 35 kilobases upstream of the HLA-C locus was associated with HIV viral load control, slower progression to AIDS and HLA-C cell surface expression levels in Caucasians." (PMID 35720328, 2022). "In summary, our results reveal how the two human AIDS viruses modulate HLA-C, a key component of the antiviral immune response." (PMID 32665270, 2020). "High levels of HLA-C mRNA and cell surface expression associate with control HIV viremia and slower progression to acquired immunodeficiency syndrome (AIDS)." (PMID 30245696, 2018). "In the analysis carried out by Carrington, individuals carrying heterozygosity for HLA-A, HLA-B, or HLA-C each showed a longer AIDS-free period compared to their homozygote locus counterparts." (PMID 20419125, 2010).
AIDS (continued). "HLA-C stability scores in HIV-1 patients according to AIDS progression." (PMID 41459481, 2025). "Although the -35CT hypothesis is very attractive to explain AIDS outcome due to the immune modulatory role of the HLA-C molecule, the complete structure of the HLA-C gene (regulatory and coding regions) has not been completely studied." (PMID 30245869, 2018). "Increased HLA-C expression was associated with delayed progression to AIDS in both African and European Americans, regardless of their distinct HLA-C frequencies and linkage relationships with HLA-B and -A." (PMID 29070683, 2018). "Since cytomegalovirus retinitis (CR) is an important cause of visual impairment among AIDS patients and HLA-C alleles have been associated with AIDS disease outcome, we typed HLA-C locus in patients with AIDS exhibiting or not CR." (PMID 30245869, 2018). "Nonetheless, the HLA-A locus is often over-shadowed by HLA-B and HLA-C in studies of HIV/AIDS." (PMID 24969460, 2014). "Substantially, the -35CC genotype (i.e., the presence of C allele at both strands in -35 position) may improve control of HIV/AIDS thanks to an augmented HLA-C surface expression resulting in an enhanced antigen presentation." (PMID 23841087, 2013). "The identification of specific variants of HLA-C as risk factors for HAND can provide a contribution both in the field of personalized medicine and for the development of new therapies, aimed at preventing and/or reducing neurocognitive damage in AIDS patients." (PMID 30298049, 2018). "It has been hypothesized that higher HLA-C expression levels might trigger HIV-1-specific responses by increasing antigen presentation to cytotoxic T lymphocytes (CTLs), binding to KIRs on NK cells, or a combination of these mechanisms, explaining the slower progression to AIDS." (PMID 29070683, 2018).
leukemia (29 papers, 2007 to 2024). A malignant (clonal) hematologic disorder, involving hematopoietic stem cells and characterized by the presence of primitive or atypical myeloid or lymphoid cells in the bone marrow and the blood. "For HLA matched donors, where iKIR-KIR ligand mismatch is less likely to occur, the presence of activating KIR2DS1 in donors has been implicated in a clinically relevant graft versus leukemia effect, modulated by the HLA-C phenotype of the donor." (PMID 33805422, 2021). "IPH2101, also known as anti-KIR1-7F9 monoclonal antibody (mAb; lirilumab is a recombinant version of this mAb), blocks common inhibitory KIRs (KIR2DL/DS-1, -2, and -3), which bind to HLA-C alleles and augment NK cell-mediated killing in HLA-C-expressing leukemia cells." (PMID 31027331, 2019). "We focused on Allo C2, since KIR2DL1 displays a more stringent recognition of HLA-C allotypes, and a greater number of HLA-C1/C1 than HLA-C2/C2 leukemia blasts, in addition to the pediatric leukemia cell line NALM-16 (HLA-C1 hemizygous) were available." (PMID 32764469, 2020). "HLA expression is high without additional stimulation of the HL-60 cell line, and exposure to IFN-γ induced upregulation of HLA-C on the MONO-MAC-1 leukemia cell lines." (PMID 31024561, 2019). "HLA-C locus mismatches have a trend of protecting against leukemia relapse." (PMID 28206973, 2017). "We have studied the probability of relapse (PR) after single-unit unrelated cord blood transplantation (UCBT) in relation to the potential graft-vs.-leukemia effect mediated by NK cells present in the umbilical cord blood (UCB) by analyzing KIR-ligand and HLA-C typing of the receptor." (PMID 28751893, 2017).
diabetes (26 papers, 2008 to 2026). "The levels of expression in the muscle tissue of the genes identified in HLA-A and HLA-C were compared among three groups for analysis: a population of Mexican origin with diabetes (Group 1) and their respective controls with positive or negative family history (Groups 2 and 3, respectively)." (PMID 35627158, 2022).
graft versus host disease (25 papers, 2011 to 2025). An immune system disorder that occurs after allogeneic hematopoietic stem cell transplant and is a reaction of donor immune cells against host tissues. "For example, the expression level of HLA-C affects the risk of graft versus host disease (GVHD) after hematopoietic stem cell transplantation (HSCT), but also the clinical outcome of human immunodeficiency virus infection and Crohn’s disease." (PMID 30192820, 2018). "The pathway enrichment for trans-eQTL egenes was largely driven by HLA genes (e.g. HLA-DRB4, HLA-C, HLA-B, HLA-DPA1, and HLA-DQA1 appear in the gene sets for graft-versus-host disease, allograft rejection, and cell adhesion molecules)." (PMID 27140173, 2016).
malaria (25 papers, 2006 to 2025). Malaria is a serious and sometimes fatal disease caused by a parasite that commonly infects a certain type of mosquito which feeds on humans. "For example, as generations of African humans survived Malaria, some individuals of African ancestry carry HLA alleles that are known to be resistant to Malaria such as HLA-B*53:01 and HLA-C*06:02." (PMID 38560292, 2024). "HLA-C*07:01 (prevalence = 26%) was associated with lower parasite prevalence (OR = 0.82, p = 0.06, p* = 0.04, q = 0.32) and lower incidence of malaria (IRR = 0.84, p = 0.04, p* = 0.02, q = 0.45) before correction." (PMID 33815410, 2021). "This is the largest cohort ever studied investigating KIR, HLA-C and malaria risk." (PMID 33632228, 2021). "The aim of this study was to compare KIR and HLA-C genetic variants that may have been selected due to differential malaria selection pressures at these sites." (PMID 33632228, 2021). "While the HLA-C*06:02 association is novel, the association of HLA-B*53:01 with a higher risk of parasitemia is notable in light of prior evidence linking this allele to protection from severe malaria." (PMID 33815410, 2021). "The aim of this study was to determine whether KIR and HLA-C genetic variants and CNV in KIR genes from 3 populations of Uganda with historically varied malaria transmission intensity have been shaped by selection pressure from falciparum malaria." (PMID 33632228, 2021). "Additionally, while it would have been interesting to explore the influence of HLA-KIR ligand pairs (i.e. KIR2DL1/HLA-C*06:02 and KIR3DL1/HLA-B*53:01) on malaria outcomes, the prevalence of both of these inhibitory KIR in our cohort was >98%." (PMID 33815410, 2021). "We were not able to directly compare malaria outcomes in HLA-C*06:02+ individuals with and without KIR2DL1, however, as KIR2DL1 was present in 99% of individuals in our cohort." (PMID 33815410, 2021). "For example, different human populations have a reciprocal relationship between the KIR and HLA-C frequencies, and the frequency of the KIR2DL3-HLA-C1 combination could be reduced in populations highly exposed to malaria, by natural selection." (PMID 23293633, 2012). "Malaria was historically common in the Mediterranean littoral, and could therefore have affected the KIR and HLA-C genotype distributions in Europe." (PMID 22412373, 2012).
preeclampsia (25 papers, 2005 to 2025). Preeclampsia is a hypertensive disorder of pregnancy that is characterized by new-onset hypertension with proteinuria presenting after 20 weeks of gestation, and depending on mild or severe forms may initially present with severe headache, visual disturbances, and hyperreflexia. "Genetic studies suggest that the combination of maternal KIRs and fetal HLA-C can alter the risk of developing placenta-related pregnancy disorders such as preeclampsia, discussed further in Section 5.4.2." (PMID 40497429, 2025). "In contrast, increased total HLA, HLA class I and, especially, HLA-C compatibility is associated with preeclampsia, suggestive for a role of HLA mismatches in immune regulation leading to uncomplicated pregnancy." (PMID 34054856, 2021). "We expect that the association of preeclampsia with certain KIR/HLA-C combinations is based on specific (paternally inherited) genes instead of general haplotypes." (PMID 34054856, 2021). "Distinguishing the Zhejiang Han is a high frequency of KIR-A and C1+HLA-C, which is a genetic combination associated with preeclampsia." (PMID 33995358, 2021). "Reproduction is also a major driver of selection, where KIR AA/C2+HLA-C genotype is associated with increased risk for developing preeclampsia." (PMID 33616658, 2021). "In this study it was shown that mothers lacking most or all activating KIR, named the KIR-AA genotype, in combination with a fetus expressing HLA-C belonging to the HLA-C2 group, were at an increased risk of preeclampsia." (PMID 31921098, 2019). "We are now undertaking a similar study at Mulago Hospital, and preliminary findings illustrate the same maternal KIR/fetal HLA-C combinations associated with preeclampsia in African women." (PMID 24184340, 2014). "In particular they suggest that mothers lacking most or all activating KIR are at a greatly increased risk of preeclampsia when the fetus possesses HLA-C belonging to the HLA-C2 group." (PMID 17288592, 2007). "For instance, it has been shown that various polymorphisms of genes coding the killer immunoglobin like receptor (KIR, expressed on decidual natural killer cells) and HLA-C expressed on the surface of extravillous trophoblasts are associated with an increased risk of preeclampsia." (PMID 40497429, 2025). "The percentage of two HLA-C matches was more than doubled compared to expected-by-chance, suggesting HLA-C compatibility between mother and child is associated with immunological processes that lead to preeclampsia." (PMID 34054856, 2021). "We observed that high HLA-C, -B, and DQB1 maternal-fetal eplet compatibility was associated with severe preeclampsia (PE) manifestation." (PMID 38022600, 2023). "High HLA-C, HLA-DQB1 and HLA-B eplet compatibility between mother and child is associated with severe manifestation of preeclampsia." (PMID 38022600, 2023). "Mismatches in HLA-B eplets: 65QIA+76ESN, 70IAO, 180E, HLA-C eplets: 193PL3, 267QE, and HLA-DRB1 eplet: 16Y were associated with a mild outcome of preeclampsia if the complication occurred." (PMID 38022600, 2023). "However, some variants of maternal KIRs and fetal HLA-C may lead to preeclampsia or miscarriage." (PMID 36496894, 2022). "Summary of the roles HLA-C, E, F and G play in normal pregnancy and how their dysregulation contributes to preeclampsia." (PMID 35571013, 2022). "We further confirmed previous literature on the importance of maternal KIR and paternally inherited fetal HLA-C combinations in the occurrence of preeclampsia." (PMID 34054856, 2021). "In comparison to uncomplicated pregnancies, pregnancies complicated with preeclampsia showed a different distribution of maternal-fetal HLA-C, HLA class I and total HLA matching, with an overall tendency towards higher compatibility." (PMID 34054856, 2021). "Accordingly, genotypes of KIR receptors on the NK cells in combination with genotypes of their ligands, HLA-C on fetal trophoblast cells have been under investigation in preeclampsia." (PMID 30483272, 2018).
preeclampsia (continued). "Indeed, we further confirmed differently distributed KIR/HLA-C genotype combinations and overall more HLA-C matches in pregnancies complicated by preeclampsia." (PMID 40416984, 2025). "Recognition of HLA-C by CD8 + T cells may be important to normal pregnancy, especially when those who lack killer cell activating receptors to interact with HLA-C are more likely to suffer from preeclampsia." (PMID 40123939, 2025). "Improper binding of KIRs to HLA-C may lead to insufficient activation of dNK cells, resulting in preeclampsia." (PMID 40034381, 2025). "Since HLA-C is highly polymorphic, certain combinations of HLA-C with KIR may hinder trophoblast invasion, increasing the risk of various pregnancy disorders, including preeclampsia, fetal growth restriction, and recurrent miscarriage." (PMID 37627278, 2023). "Moreover, a significantly higher extent of total HLA compatibility in preeclampsia suggests a broader contribution than HLA-C or HLA class I alone." (PMID 34054856, 2021). "The largest cohort study to date on specific HLA alleles and the risk on preeclampsia did not include the analysis of HLA-C and fully split up the analysis of the amount of total maternal-fetal HLA matches." (PMID 34054856, 2021). "Additionally, certain combinations of alleles of the fetal HLA-C gene and maternal killer immunoglobulin like receptor (KIR) on NK cells have been shown to have an increased incidence of preeclampsia." (PMID 28130428, 2017). "Selective forces other than infection may also be entertained, including autoimmunity and reproduction, illustrated by the link between preeclampsia and combinations of HLA-C in the fetus and KIR in the mother." (PMID 16132082, 2005). "An example within this notion is the established correlation between the recurrence of miscarriages, FGR or preeclampsia and (i) the KIR repertoire skewing, (ii) KIR/HLA-C match or mismatch, and the (iii) changes in the interval between pregnancies and partners." (PMID 31379803, 2019). "Studies evaluating the expression patterns of HLA-C and activating versus inhibitory KIRs in the placentas of patients with mild vs severe preeclampsia in contrast to those without preeclampsia across different ethnic groups may be informative." (PMID 35571013, 2022).
lung carcinoma (24 papers, 2012 to 2025). "In addition, from the set of 49 lung cancer genes, we found that HLA-C had the fourth, HLA-B had the seventh and HLA-A had the eighth highest frequency of alternative splicing." (PMID 39358601, 2024). "Notably, HLA-B and HLA-C are linked to smoking-associated ailments, including COPD and lung cancer." (PMID 38672772, 2024). "As an example, the Jcomp score across the 11 lung cancer tissues was positively correlated with the expression of genes coding MHC-class I protein (B2M, HLA-A, HLA-B, and HLA-C), which are among the biomarkers for immunotherapy response." (PMID 40170080, 2025).
systemic lupus erythematosus (23 papers, 2008 to 2025). An autoimmune multi-organ disease typically associated with vasculopathy and autoantibody production. "On this line, the MHC class II molecules HLA-DQB1 and HLA-DRB1, along with the MCH class I HLA-C, have been recently associated with resistance to systemic autoimmune diseases, such as systemic sclerosis, systemic lupus erythematosus and rheumatoid arthritis." (PMID 31511551, 2019). "HLA-C variants are also associated with increased susceptibility to systemic lupus erythematosus." (PMID 36134954, 2022). "Other immune disorders in which HLA-C participates are systemic lupus erythematosus and progressive systemic scleroderma, suggesting that these pathologies could be linked to variants of KIR receptors." (PMID 37465164, 2023).